UCA1 (urothelial cancer associated 1)
Diseases named in the same sentence as UCA1 in open-access papers (continued):
Sharing a sentence is not in itself a finding about the gene and the disease.
endometriosis (continued). "Since endometriosis shares several features with cancer, we investigated the possible involvement of cancer-related lncRNAs in endometriosis, including UCA1, GAS5 and PTENP1." (PMID 35901079, 2022). "Based on those results, we confirmed the possible involvements of three functional SNPs in UCA1, especially the two-locus hyplotypes among these three, in the development of endometriosis." (PMID 35901079, 2022). "In our study, three of the four sequences we studied (UCA1, MALAT1, TC0101441) were found to be statistically insignificant from the point of view of endometriosis risk." (PMID 36232884, 2022). "UCA1 was downregulated in the ectopic endometrium of a cohort of 98 endometriosis patients compared to 28 healthy controls." (PMID 34638965, 2021). "In this study, we found that the expression of UCA1 in the eutopic endometrium of patients with endometriosis was higher than that in the normal endometrium by qRT-PCR." (PMID 33680939, 2020). "In this study, qRT-PCR analysis showed that the expression level of UCA1 in the eutopic endometrium of patients with endometriosis was significantly higher than that in the normal endometrium." (PMID 33680939, 2020). "Future animal research and bioinformatics evaluation will help to determine the mechanism of UCA1 in endometriosis." (PMID 33680939, 2020). "qRT-PCR revealed that the expression of lncRNA UCA1 was significantly higher in the eutopic endometrium of patients with endometriosis (0.965 ± 0.105) than in normal endometrial tissues (0.196 ± 0.079) (P<0.01)." (PMID 33680939, 2020). "Knockout of the UCA1 gene inhibits the proliferation of ESCs, promotes apoptosis, promotes autophagy and participates in the occurrence and development of endometriosis." (PMID 33680939, 2020). "Recent research indicates that UCA1 participates in the pathogenesis of endometriosis." (PMID 36232884, 2022). "It is known that UCA1 may be involved in the occurrence and development of endometriosis by promoting cell proliferation and inhibiting apoptosis." (PMID 36232884, 2022). "The role of UCA1 in the pathogenesis of endometriosis needs further study." (PMID 33680939, 2020). "In general, our data suggest that all the risk-associated haplotypes in UCA1 can generate more stable RNA products, some may even change their RNA structures, leading to higher expression UCA1 levels in endometrial tissues during the development of endometriosis." (PMID 35901079, 2022). "This study aimed to analyze the level of expression of four long non-coding RNA (UCA1, MALAT1, TC0101441, and H19) in endometriosis." (PMID 36232884, 2022). "Thus, we have focused on whether UCA1 has significance in the study of endometriosis." (PMID 33680939, 2020). "However, there are no published reports on the role of UCA1 in endometriosis (EMS)." (PMID 33680939, 2020).
cholangiocarcinoma (6 papers, 2017 to 2023). A carcinoma that arises from the intrahepatic biliary tree (intrahepatic cholangiocarcinoma) or from the junction, or adjacent to the junction, of the right and left hepatic ducts (hilar cholangiocarcinoma). "In cholangiocarcinoma, UCA1 upregulates chloride intracellular channel 1 (CLIC1) expression by inhibiting miR-122 expression and activating the ERK/MAPK signaling pathway to promote the metastasis of malignant cells." (PMID 33777227, 2021). "On the other hand, overexpressed lncRNA UCA1 in cholangiocarcinoma (CCA) showed that it could act as an independent prognostic factor in CCA patients." (PMID 33936199, 2021).
glioblastoma (6 papers, 2014 to 2021). The most malignant astrocytic tumor (WHO grade IV). "In glioblastoma, CXCL14 in glioblastoma-associated stromal cells could induce glycolysis and invasion of glioma cells by regulating the UCA1/miR-182/PFKFB2 axis." (PMID 32083005, 2020).
chronic myeloid leukemia (5 papers, 2017 to 2024). "Furthermore, UCA1 also facilitates the progression of chronic myeloid leukemia and AML." (PMID 33969374, 2021). "In chronic myeloid leukemia (CML) K562 cells, the upregulation of lncRNA UCA1 was shown to increase the MDR transporter ABCB1 expression and induce resistance to the ABCB1 substrate imatinib." (PMID 39403602, 2024).
endometrial cancer (5 papers, 2017 to 2025). Primary or metastatic malignant neoplasm involving the endometrium (mucous membrane that lines the endometrial cavity). "While the risk of endometrial cancer increases significantly with age, low UCA1 levels may be a protective factor." (PMID 41226033, 2025). "After observing the positive correlation of UCA1 with the LNM of endometrial cancer, scholars have confirmed that the deficiency in UCA1 could reduce migration and invasion." (PMID 29368602, 2018). "When comparing patients with endometrial cancer and controls, age and UCA1 levels were found to be particularly discriminatory." (PMID 41226033, 2025). "UCA1, conversely, has shown context-dependent behavior—acting as an oncogenic driver in ovarian and cervical carcinomas, but with reports of downregulation in endometrial cancer, suggesting a complex role in endometrial tumorigenesis." (PMID 41226033, 2025). "Inhibition of UCA1 suppressed the endometrial cancer cell migration and invasion." (PMID 29207643, 2017).
metastatic tumors (5 papers, 2016 to 2024). "Further, to identify the role of the factors in motifs with good predictive power (CDK4/SNHG5/hsa-let-7a-3p and UCA1/AKT1/hsa-miR-125b-1) in the regulation of various metastatic tumors, we used Target Mine web server and selected BH method (Benjamini-Hochberg) for P-value adjustment." (PMID 32703153, 2020). "Furthermore, UCA1 concentrations were measured to be even more elevated in the blood samples of patients in advanced stages, and women with lymph node and distant organ metastatic disease." (PMID 38534790, 2024). "The results showed that the 7901-Lv-UCA1 group formed more nodes compared with the 7901-Lv-NC group, while the BGC-Lv-shUCA1 group exhibited less nodes compared to the BGC-Lv-sh control group, and the nodes were proved to be metastatic tumors by HE staining." (PMID 30464170, 2018).
preeclampsia (5 papers, 2021 to 2025). Preeclampsia is a hypertensive disorder of pregnancy that is characterized by new-onset hypertension with proteinuria presenting after 20 weeks of gestation, and depending on mild or severe forms may initially present with severe headache, visual disturbances, and hyperreflexia. "Taken together, these observations suggest a role for the evolution-related UCA1 in the HIF1α-induced adaptive pathogenic mechanism of preeclampsia, promoting the survival of hypoxic trophoblasts and injuring maternal endothelial cells." (PMID 36160709, 2022). "In addition to methylation alterations, some long non-coding RNA and miRNA are important in fusion and altered in preeclampsia, with one of the most documented being UCA1 (Urothelial Cancer-Associated 1)." (PMID 40243430, 2025). "As noncoding RNAs are an important part of evolutionary genetics and have been confirmed to play regulatory roles in preeclampsia, seven lncRNAs reported to be associated with hypoxia were selected, including UCA1, EFNA3, H19, MALAT1, HOTAIR, FALEC, and HAS2-AS1." (PMID 36160709, 2022). "This study proposes a novel theory to elucidate how placental dysfunction may cause pathophysiological features of preeclampsia, namely, the human-specific UCA1-mediated adaptive responses." (PMID 36160709, 2022). "In the present study, we reported that urothelial cancer associated 1 (UCA1), a hypoxia-responsive long noncoding RNA (lncRNA), was a potentially critical mediator linking the HIF1α-induced placental hypoxia adaptation to distal maternal endothelial injury, leading to the occurrence of preeclampsia." (PMID 36160709, 2022). "Then, UCA1 was confirmed to be a hypoxia-responsive and HIF1α-regulated lncRNA, similar to other studies in cancers, suggesting that UCA1 is a downstream molecule of the HIF1α pathway and hypoxia responses in women with preeclampsia." (PMID 36160709, 2022). "Based on this knowledge, we inferred that the elevated UCA1 expression in preeclampsia represents an incomplete compensatory mechanism secondary to placental ischemia and hypoxia instead of the cause of impaired trophoblast biofunction." (PMID 36160709, 2022). "UCA1 is a human-specific lncRNA regulated by HIF1α and is involved in the pathogenesis of preeclampsia." (PMID 36160709, 2022). "Our study confirmed what was published previously, where UCA1 expression is increased in preeclampsia placentas." (PMID 35740273, 2022). "Considering the instability of cell-free lncRNAs and the stable existence of UCA1 in exosomes reported in previous studies on cancers, serum exosomal UCA1 levels were measured and were higher in patients with preeclampsia." (PMID 36160709, 2022). "Six lncRNAs were validated and differentially expressed (p < 0.05) in the preeclampsia and control placentas: UCA1 and HCG4 were found upregulated, and LOC101927355, LINC00551, PART1, and NRAD1 downregulated." (PMID 35740273, 2022). "Meanwhile, preeclampsia was also reported in humans and great apes, which showed high UCA1 similarity." (PMID 36160709, 2022). "Genome-wide transcriptomic studies showing up-regulation of UCA1 either in preeclampsia or intrauterine growth retardation." (PMID 34055770, 2021). "We reported that urothelial cancer associated 1 (UCA1) is a potential mediator because it is a human-specific long noncoding RNA (lncRNA) that is upregulated in placental tissues and maternal serum from women with preeclampsia and is regulated by HIF1α." (PMID 36160709, 2022). "A differential expression analysis with a publicly available microarray dataset (GSE75010) was performed to determine the UCA1 expression level in tissues from women with preeclampsia, and the results indicated that UCA1 expression was increased in preeclamptic placentae." (PMID 36160709, 2022).
preeclampsia (continued). "Therefore, this study provides an evolutionary perspective and insights into the pathogenesis of preeclampsia, namely, HIF1α/UCA1-induced adaptive responses that link the placental hypoxia adaptation to distant endothelial injury." (PMID 36160709, 2022). "Hence, exosomal UCA1 expression was increased in the maternal circulation of women with preeclampsia and the supernatant of hypoxic trophoblast cells, implying that UCA1 might be a mediator connecting trophoblasts and maternal peripheral cells." (PMID 36160709, 2022). "Therefore, we assumed that UCA1 may have dual functions in preeclampsia and other complex pathological environments." (PMID 36160709, 2022). "In the case of the lncRNAs UCA1 and HCG4, their expression was upregulated in the preeclampsia placentas (p = 0.035 and p = 0.012, respectively) compared to the control group." (PMID 35740273, 2022). "In the present study, the expression of human-specific UCA1 showed the same change as HIF1α expression in normal pregnancy and preeclampsia: high expression in early gestation that dwindled during normal pregnancy but was upregulated in the preeclamptic placenta again." (PMID 36160709, 2022).
thyroid cancer (5 papers, 2017 to 2022). "Conversely, UCA1 activates the Hippo signaling pathway by downregulating miR-15a expression and increasing cell viability and EMT in human thyroid cancer." (PMID 33777227, 2021). "In addition, UCA1 promotes the viability and EMT of TPC-1 cells by competing with miR-15a and activating the Hippo and JNK signaling pathways in human thyroid cancer." (PMID 33777227, 2021).
tongue cancer (5 papers, 2017 to 2025). A malignant neoplasm affecting the tongue. "LncRNA UCA-1 expression is induced upon TGF-β treatment in tongue cancer cells, and it promotes EMT and invasion by sponging miR-124 to promote JAG1/Notch1 signaling." (PMID 40594481, 2025). "Yang demonstrated that the lncRNA UCA1 promoted tongue cancer cell proliferation and metastasis and inhibited their apoptosis through affecting the activation of the WNT/β-catenin signaling pathway." (PMID 29970910, 2018). "Other lncRNAs that have been reported in oral cancer include MEG3, which was down-regulated in tongue cancer, and UCA1, which was up-regulated in tongue cancer." (PMID 28415559, 2017).
gallbladder cancer (4 papers, 2017 to 2019). "In gallbladder cancer cells, UCA1 interacted with Brahma related gene 1 (BRG1) of the chromatin SWI/SNF remodeling complex and prevented its binding to the p21 promoter locus." (PMID 30441811, 2018). "In this study, we found that UCA1 was significantly overexpressed in gallbladder cancer (GBC) and positively correlated with tumor size, lymph node metastasis, TNM stage and short survival time." (PMID 28624787, 2017). "Interestingly, a recent evaluation of tumor-derived exosomes in cancer diagnosis showed that UCA1 is not only expressed in gallbladder cancer exosomes, but also in exosomes isolated from the serum of CRC patients." (PMID 30441811, 2018). "MEG3 and UCA1 could both target Enhancer of Zeste Homolog 2 (EZH2), despite their differential roles in gallbladder cancer." (PMID 31297033, 2019).
leukemia (4 papers, 2015 to 2022). A malignant (clonal) hematologic disorder, involving hematopoietic stem cells and characterized by the presence of primitive or atypical myeloid or lymphoid cells in the bone marrow and the blood. "In component #7, a lncRNA UCA1 (8th) is found to be related with Leukemia, Myeloid, Chronic-Phase (3rd), which is verified by the database LncRNADisease." (PMID 35249529, 2022). "The association of lncRNAs with several subtypes of leukemia, such as MEG3, IRAIN, and UCA1 related to AML and ANRIL, LUNAR1, in ALL, increase the possibility to use them as biomarkers for the diagnosis, prognosis, and treatment (to provide a target) for the different subtypes of this disease." (PMID 30744139, 2019).
liver diseases (4 papers, 2020 to 2024). "The levels of serum HULC, MALAT1, Linc00152, PTTG3P, SPRY4-IT1, UBE2CP3, and UCA1 were significantly higher in HCC patients than in patients with benign liver diseases and healthy controls, whereas serum PTENP1 was significantly decreased in HCC patients compared with healthy participants." (PMID 32733618, 2020).
metastatic melanoma (4 papers, 2017 to 2021). A melanoma that has spread from its primary site to another anatomic site. "LINC00518 and LINC00520 were each found to be independent risk factors for metastatic melanoma patient survival and the network motif UCA1/hsa-miR-125b-1/AKT1 has an 88% chance of correctly identifying a TCGA sample as metastatic melanoma." (PMID 35008286, 2021). "The results suggested a prognostic value of motif 3 (UCA1/AKT1/hsa-miR-125b-1) for discriminating metastatic and non-metastatic melanoma phenotypes with a high prediction accuracy (ACC = 0.88)." (PMID 32703153, 2020).
multiple myeloma (4 papers, 2017 to 2023). "miR-1271-5p, sponged by lncRNA UCA1, contributes to apoptosis and inhibits the proliferation capacity in multiple myeloma." (PMID 32948241, 2020). "A recent research demonstrated that over-expressed UCA1 contributes to poor prognosis in patients with multiple myeloma." (PMID 29221199, 2017).
pancreatic ductal adenocarcinoma (4 papers, 2020 to 2025). An infiltrating adenocarcinoma that arises from the epithelial cells of the pancreas. "UCA1 expression can be upregulated by oncogenic KRAS, a major driver mutation in pancreatic ductal adenocarcinoma." (PMID 41080752, 2025). "In pancreatic ductal adenocarcinoma (PDAC), lncRNA UCA1 regulated miR-590-3p to increase the expression of oncogenic Kirsten rat sarcoma viral oncogene homolog (KRAS) protein, and KRAS itself can promote lncRNA UCA1 expression." (PMID 33936199, 2021). "UCA1 functions as a competing endogenous RNA (ceRNA) to increase the expression of KRAS via sponging miR-590–3p in pancreatic ductal adenocarcinoma; KRAS, in turn, promotes the UCA1 expression." (PMID 34134622, 2021).
psoriasis (4 papers, 2022 to 2025). An autoimmune condition characterized by red, well-delineated plaques with silvery scales that are usually on the extensor surfaces and scalp. "Our findings suggest that lncRNA UCA1 promotes keratinocyte-driven inflammation in psoriasis by targeting and inhibiting METTL14 protein and then activating the HIF-1α/STAT3 and NF-κB signaling pathways." (PMID 37076497, 2023). "In this study, we analyzed the transcriptome of psoriatic skin and the relationship between psoriasis development and UCA1." (PMID 37076497, 2023). "Taken together, this work indicates that UCA1 positively regulates keratinocyte-driven inflammation and psoriasis development by binding to METTL14, and activating HIF-1α and NF-κB signaling pathway." (PMID 37076497, 2023). "Prominent skin-expressing lncRNAs that were upregulated in both psoriasis and atopic dermatitis lesional skin include UCA1 and SPRR2C (small proline rich protein 2C)." (PMID 35559048, 2022). "Initially named for its high expression in bladder cancer cells, UCA1 has now gained more attention regarding its role in psoriasis." (PMID 35559048, 2022). "UCA1 was identified as a psoriasis-related lncRNA that highly expressed in psoriatic lesions." (PMID 37076497, 2023). "In psoriasis, METTL14 interacts with UCA1 to regulate the HIF‐1α/NF‐κB axis, while also modulating the SOCS3/STAT3 pathway to attenuate IL‐6‐mediated inflammation." (PMID 41316520, 2025). "Through its interaction with METTL14, UCA1 activates both HIF‐1α and NF‐κB signaling pathways, consequently promoting keratinocyte‐mediated inflammatory responses and contributing to psoriasis pathogenesis." (PMID 41316520, 2025). "Consistent with this, UCA1 was markedly upregulated in primary human epidermal keratinocytes (HEK) and immortalized human keratinocytes HaCaT stimulated with IL17 and/or tumor necrosis factor alpha (TNF-α), which was accompanied by a psoriasis-like inflammatory response (Figure." (PMID 37076497, 2023).
rectal cancer (4 papers, 2018 to 2022). A primary or metastatic malignant neoplasm that affects the rectum. "A microarray analysis indicated the RNA expression of five genes (NDRG1, ERRFI1, H19, MPZL3, and UCA1) was highly increased in radio-resistant rectal cancer cell lines." (PMID 29801473, 2018). "The expression levels of the onco-lncRNAs, including CCAT1, LOC152578, UCA1, CRNDE, PVT1, MALAT1, XLOC_000303, XLOC_006844, BCAR4, and HOTAIR, were significantly increased in the rectal cancer patients compared to the control group." (PMID 35654932, 2022).
renal cell carcinoma (4 papers, 2017 to 2021). "We have noticed that UCA1 gathered both in the cytoplasm and nuclear region in renal cell carcinoma cells." (PMID 29221199, 2017). "Upregulated SOX4 by UCA1 contributes to proliferation and invasion in renal cell carcinoma." (PMID 30922402, 2019).